COL1A1 (collagen type I alpha 1 chain)
Diseases named in the same sentence as COL1A1 in open-access papers (continued):
Sharing a sentence is not in itself a finding about the gene and the disease.
gastric cancer (continued). "Our analysis, thus, showed that abnormal expression of BMP1, COL1A1, STAT3, GATA6, SOX2 and FOXA2 forms an ubiquitous molecular signature of gastric cancer patients in Southwestern Taiwan." (PMID 29720137, 2018). "Four hub genes with worse overall survival (OS) of gastric cancer patients were detected and the Kaplan Meier-plotter was applied to visualize them, including BGN, MMP2, COL1A1 and FN1." (PMID 29050278, 2017). "COL1A1 has also been reported to regulate proliferation and migration in BGC-823 gastric cancer cells." (PMID 27894325, 2016). "Consistent with previous reports, the present study demonstrated that COL1A1 and COL1A2 mRNA expression levels were highly expressed in gastric cancer specimens compared to normal gastric epithelium by real-time quantitative PCR analysis." (PMID 27894325, 2016). "The correlations between COL1A1 and COL1A2 expression and clinicopathological parameters were analyzed in 45 gastric cancer patients undergoing surgery." (PMID 27894325, 2016). "Then, analysis was performed to correlate COL1A1 and COL1A2 mRNA expression and clinicopathological parameters and overall survival time in gastric cancer." (PMID 27894325, 2016). "In the present study, we demonstrate the relationships between clinicopathological parameters and overall survival time and COL1A1 and COL1A2 mRNA expression in gastric cancer." (PMID 27894325, 2016). "In addition, COL1A1 might be a potential biomarker for early gastric cancer diagnosis." (PMID 27894325, 2016). "In addition, the expression of COL1A1 and NCAM1 was confirmed in gastric cancer tissues and were associated with gastric cancer invasion; however, it remains unknown which miRNA(s) regulate their expression in gastric cancer." (PMID 25860484, 2015). "Further studies are required to confirm the expression status of COL1A1 and NCAM1 proteins as potential biomarkers for early diagnosis and prediction of gastric cancer progression." (PMID 25860484, 2015). "In another gastric cancer study, RUNX2 was found to promote metastasis through the upregulation of COL1A1 expression, with patients displaying elevated levels of both RUNX2 and COL1A1 experiencing reduced survival times, thereby indicating a poor prognosis." (PMID 38430423, 2024). "Besides, high expression of five genes, POSTN, COL5A2, COL1A1, FN1, and MMP2, was revealed by Kaplan–Meier survival curve analysis to suggest a poor prognosis for gastric cancer patients." (PMID 37461041, 2023). "Together, these studies illuminate that COL1A1 and COL5A2 may not only be reliable biomarkers of gastric cancer cell proliferation and metastasis, and also key predictors of poor prognosis in patients with gastric cancer." (PMID 36471693, 2022). "Hence the module analysis strengthened the connection of the six CAF markers: COL1A1, COL1A2, COL3A1, COL5A1, FN1 and, SPARC, with the 3 KEGG pathways: ECM-receptor interaction, focal adhesion and, PI3K-Akt signaling pathway in gastric cancer." (PMID 35739492, 2022). "In addition, COL1A1 has been identified as an oncogene that is involved in the carcinogenesis of colorectal cancer, gastric cancer (GC), and oral cancer and could be used as a potential therapeutic target." (PMID 35186916, 2022). "One limitation to the study may be that only the TIDE algorithm predicted a poor prognostic impact for CAF infiltration in COL1A1, COL5A1, ITGA4, EMILIN1, and TSPAN9 multivariate Cox model in gastric cancer." (PMID 35739492, 2022). "Results showed that the linear form of COL1A1 could be amplified from both cDNA and gDNA in BGC-823 and AGS gastric cancer cells, while circCOL1A1 could only be amplified in cDNA." (PMID 34631898, 2021). "Our study identified COL1A1 and COL1A2 as potential gastric cancer prognostic biomarkers." (PMID 32509452, 2020). "The group of Li J also supposed that COL1A1 and COL1A2 might predict poor clinical outcomes in gastric cancer patients." (PMID 31409759, 2019).
gastric cancer (continued). "In this study, a total of 971 DEGs and 15 hub genes were selected, and BGN, MMP2, COL1A1 and FN1 might be the core genes of gastric cancer." (PMID 29050278, 2017). "In addition, qRT- PCR and Western blot data showed an increase in COL1A1 and decrease in NCAM1 mRNA and protein levels in gastric cancer tissues." (PMID 25860484, 2015). "However, the expression of COL1A1 and COL1A2 in malignant, premalignant, and normal gastric tissues and their clinical significances in gastric cancer have not been elucidated." (PMID 27894325, 2016).
fibrosis (66 papers, 2010 to 2025). the formation of excess fibrous connective tissue in an organ or tissue in a reparative or reactive process. "Our results showed that Nano-CuO exposure induced remarkable increases in the levels of α-SMA, COL1A1, and fibronectin proteins, suggesting that Nano-CuO exposure caused fibrosis in mouse lungs." (PMID 39030581, 2024). "However, genes associated with cartilage fibrosis (such as Sparc and Col1a1) and hypertrophy (e.g., Ibsp, Bmp2, Mmp13, and Matn4) presented the highest expression levels at 6 weeks." (PMID 40722047, 2025). "Thus, Fas deficiency in Dermo1-Cre– and Col1a1-expressing fibroblasts impedes fibroblast elimination from lung tissues during homeostatic resolution of bleomycin-induced fibrosis." (PMID 33290280, 2020). "The Pde4d, Col1a1, and Acta2 were also upregulated in carbon tetrachloride–induced (CCl4-induced) fibrosis." (PMID 41196648, 2025). "Excessive accumulation of COL1A1 distorts liver architecture, impairs function, and marks the transition to advanced fibrosis and cirrhosis." (PMID 40572736, 2025). "Compared with those of 12- and 32-week-old mice, the kidneys of the model mice exhibited prominent fibrosis characteristics, accompanied by numerous fibrous septa and collagen deposition, increased COL1A1 expression, and decreased MMP9 expression." (PMID 39661589, 2024). "Canonical transcriptional changes in steatohepatitis include the activation of TNFA, while induction of the alpha‐1 subunit of type 1 collagen (COL1A1) is characteristic of fibrosis." (PMID 37962490, 2023). "Next, we found that in the CCl4-induced fibrosis model, the mRNA expression of Col1a1, Col3a1, and α-SMA increase, while these elevations were abrogated in the MlkliΔEC/iΔEC group, as shown by RT-qPCR." (PMID 37511074, 2023). "Hepatic CCN2 expression was significantly induced in NASH patients with F3–F4 fibrosis and was positively correlated with hepatic Col1A1, Col1A2, Col3A1, or αSMA expression." (PMID 37629004, 2023). "Some studies have shown that excessive scar fibrosis occurs when expression of ECM proteins (such as pro-COL1A1) increase." (PMID 35682793, 2022). "Surprisingly, the hearts of both W and WRF rats showed increased Collagen 1 expression, i.e., W rat heart exhibited signs of fibrosis despite any increase in Col1a1 and Col1a2 expression." (PMID 35236346, 2022). "This onset in the features of T2DM with circadian disruption is found to coincide with the presence of myocardial perivascular fibrosis and an increase in Col1a1 expression." (PMID 33958671, 2021). "Collectively, these data indicate CREBBP/EP300 is a highly associated pathway in localized human fibrosis that controls key aspects of myofibroblast phenotype and function, including ACTA2 and COL1A1 gene expression and cell contractility." (PMID 32759223, 2020). "This is consistent with the observation that the expression of COL1A1 was positively correlated with fibrosis and the patients with a high COL1A1 expression needed HTx in a much shorter period than those with a low COL1A1 expression." (PMID 31902369, 2020). "COL1A1 is a subunit of type 1 collagen, which accumulates in the liver during fibrosis and cirrhosis." (PMID 30526554, 2018). "Moreover, USP28 knockout in cardiomyocytes mitigated cardiac fibrosis, as assessed by Masson's trichome staining and qPCR assay on mRNA levels of Tgfb and Col1a1." (PMID 39431010, 2024). "Finally, the disease gene-association analysis on the DEGs without the respiratory tract disease filter showed that six DEGs (namely, ACTG2, AGER, COL1A1, COL3A1, IGF1, and SPP1) were associated with fibrosis." (PMID 39944354, 2024). "Furthermore, Mettl1 overexpression induced cardiac fibrosis, as demonstrated by Masson's staining, along with a remarkable increase in mRNA expression of fibrotic genes, as well as increased protein levels of Col1a1 and α‐SMA." (PMID 38810124, 2024).
fibrosis (continued). "Through histological, protein content, and transcript analysis approaches, we found that cardiac fibrosis‐related genes partly change, with significant TS‐associated increases in Tgfb1, but without changes in Col1a1 and Fn1." (PMID 36695670, 2023). "Meanwhile, the cardiac fibrosis is also promoted with the featured phenotype of interstitial and perivascular fibrosis, signatured with upregulated Col1a1, Col3a1 and Tgfb expression, along with a significant increase of MMP-2 and surge upregulated active-MMP-9." (PMID 36834504, 2023). "The study was also driven by the hypothesis that col1a1 degradation is attenuated in fibrosis, using CKD as a prototypic example for fibrotic disease." (PMID 35050988, 2021). "Cluster 3 showed the highest COL1A1 expression and was enriched with cells from fibrosis patients." (PMID 32317643, 2020). "Compared with sham rats, 5/6NX rats showed significantly increased levels of SCr, BUN, and HA, as well as increased fibrosis area, glomerular sclerosis index, and fibrotic marker levels (COL1A1, VIM, and ACTA2), suggesting that the 5/6NX rat model was effective." (PMID 32854194, 2020). "The extent of liver granuloma and fibrosis was evaluated by monitoring the liver aspect, collagen deposition (Sirius red staining), and HSCs activation [high RNA and protein expression levels of Acta2 (which encodes α-SMA), Col1a1, and Col3a1]." (PMID 29321784, 2017). "The observed decrease in miR-26 expression may help explain the increased expression of COL1A1 in the adolescent Infarct samples and represents a valuable molecular target for up-regulation to prevent adverse cardiac fibrosis and reduce infarct size post-infarct setting in adults." (PMID 32587529, 2020). "Compared to the low-fibrosis group, expression of COL1A1 (P = 0.042) and COL1A2 (P = 0.032) was significantly higher in the high-fibrosis group, whereas COL4A4 expression (P = 0.041) was lower." (PMID 41049608, 2025). "We overexpressed miR-486-5p in MRC-5 cells, a cell line commonly used in fibrosis research, and observed a decrease in the expression of fibrosis genes, including Fn, α-SMA, vimentin, COL1A1, and COL3A1." (PMID 40692863, 2025). "Fibrosis is characterized by expansion and remodeling of the extracellular matrix (ECM) as well as the upregulated expression of type I collagen alpha 1 (COL1A1), type III collagen alpha 1 (COL3A1), etc.." (PMID 38710658, 2024). "In our findings, the suppression of ALKBH5 promoted the expression of COL3A1, COL1A1 and ELN, and these increased ECM components were subsequently secreted and deposited within the dermis, culminating in dermal fibrosis and scar hyperplasia." (PMID 39233335, 2024). "RT-PCR also demonstrated a substantial upregulation in the mRNA expression levels of ADAM19 and fibrosis-related genes (COL1A1, COL1A2, and FN1) in the skin tissues of the HOCl-induced fibrosis mouse model compared to controls." (PMID 39716051, 2024). "The EPRS1-positive area was positively correlated with fibrosis, proteinuria, BUN levels, and Col1a1 mRNA levels and negatively correlated with creatinine clearance." (PMID 39623092, 2024). "In contrast, Notch signalling has also been reported to directly upregulate COL1A1 and COL1A2 promoter activity through a Hes1‐dependent mechanism in airway subepithelial fibrosis." (PMID 34363303, 2021). "In this context, we have observed a significant reduction of COL1A1 and TGFB1 gene expressions through the addition of 2 μM amphotericin B in our fibrosis model with primary NHDFs supplemented with TGF-β1." (PMID 33096778, 2020). "Consistently, hepatic fibrosis markers; α-smooth muscle actin (α-SMA) and collagen type I alpha 1 (COL1A1), were highly expressed in the mice fed the MCD diet." (PMID 32331258, 2020). "Co-cultures of PHH1 and NPC1, which spontaneously and reproducibly deposited fibrillary extracellular matrix exemplified by COL1A1 staining, were used as a screening platform for anti-NASH/fibrosis drugs." (PMID 32295224, 2020).
fibrosis (continued). "Some of the most significantly activated canonical pathways included hepatic fibrosis/hepatic stellate cell activation (CD14, COL1A1, FGFR2, IGFBP3, MMP2, and TGFBR1), and p38 MAPK signaling pathways (CREB1, PLA2G2A, TGFBR1)." (PMID 20540791, 2010). "Importantly, GDF10 expression was significantly elevated in human metabolic liver disease and fibrosis samples, showing strong correlation with classic fibrosis markers (ACTA2, COL1A1)." (PMID 41281741, 2025). "The results revealed that COL1A1 expression was significantly upregulated, while COL2A1 expression was downregulated in the Model group compared to the Blank control group, indicating that puncture-induced modeling increased disc fibrosis and impaired NP functionality." (PMID 40356987, 2025). "Indeed, exposure of PCLS from patients with fibrosis or end-stage cirrhosis to Ac-6-FP resulted in a decrease in MAIT cell activation and reduced the expression of fibrogenic genes, including COL1A1 and COL1A2, ACTA2, and TGFB1, together with the number of fibrogenic cells." (PMID 37005415, 2023). "Indeed, histology showed submucosal fibrosis, but the markers of myofibroblast activation (CTGF and COL1A1) were not increased compared to controls suggesting the myofibroblasts were no longer activated." (PMID 33302890, 2020).
osteoporosis (66 papers, 2007 to 2025). A condition of reduced bone mass, with decreased cortical thickness and a decrease in the number and size of the trabeculae of cancellous bone (but normal chemical composition), resulting in increased fracture incidence. "Single nucleotide polymorphisms in genes critical for bone homeostasis, including ALPL, DKK1, PHEX, and COL1A1, are associated with osteoporosis and related skeletal pathologies in humans." (PMID 40961770, 2025). "Our results are also supported by the Dubbo Osteoporosis Epidemiology Study, which evaluated COL1A1 Sp1-binding-site polymorphisms (rs1800012) in 809 postmenopausal women over a 30-year period." (PMID 40507792, 2025). "While commonly linked to ageing and environmental factors, osteoporosis can also result from Mendelian monogenic disorders, with mutations in genes such as COL1A1 and COL1A2 impairing bone integrity." (PMID 40772209, 2025). "Our RNA-seq results showed that the expression of the Col1A1, Col1A2, and Vdr genes associated with osteoporosis (as revealed by OMIM disease enrichment analysis) was decreased by H2O2." (PMID 37464093, 2023). "Because of this, we decided to explore variants in the COL1A1 gene that have been studied in relation to osteoporosis and fractures." (PMID 35264229, 2022). "Polymorphisms of genes such as VDR, ER, OPG, COL1A1 and TNFα are associated with osteoporosis and fracture risk." (PMID 36362662, 2022). "According to CTD, COL1A1 was closely associated with osteoporosis and atherosclerosis and it had the highest inference score and reference count." (PMID 35937806, 2022). "Some research focused on the COL1A1 polymorphisms associates them significantly with low bone mineral density, osteoporosis, increased fracture risk, and osteonecrosis." (PMID 35264229, 2022). "The association between COL1A1 rs1800012 polymorphism and the risk of osteoporosis as well as osteoporosis-induced fracture has been well established." (PMID 29088884, 2017). "A latest meta-analysis contained 1557 subjects has indicated that GG genotype in COL1A1 rs1800012 polymorphism shows a protective effect to osteoporosis risk in post-menopausal women." (PMID 29088884, 2017). "The aim of this investigation was to evaluate potential association between COL1A1 gene polymorphism and osteoporosis in Kazakh postmenopausal women." (PMID 29805881, 2014). "Osteoblast-specific overexpression of Krm2 in transgenic mice (Col1a1-Krm2) results in severe osteoporosis that is associated with an impaired osteoblast maturation and bone formation as well as increased bone resorption." (PMID 25061805, 2014). "Data analysis of 1245G>T polymorphism in COL1A1 gene in the group of women with osteopenia and osteoporosis revealed deviation from Hardy-Weinberg equilibrium." (PMID 29805881, 2014). "However, common COL1A1 alleles resulting in homotrimeric type I collagen are associated with osteoporosis." (PMID 36106514, 2022). "This may explain that P12 had a mild OI phenotype, due to the presence of frameshift COL1A1 mutation, but severe osteoporosis." (PMID 34394176, 2021). "Present results further elucidate the inheritance pattern of HESX1 variants and recommend assessing the clinical impact of variants located in C-terminal propeptide of COL1A1 gene for their potential association with rare recessive and early onset forms of osteoporosis." (PMID 33451138, 2021). "In addition, osteoporosis is strongly associated with genetic components of type 1 collagen such as COL1A1 and COL1A2." (PMID 32353054, 2020). "Moreover, osteoporosis is strongly associated with genetic components of type 1 collagen such as COL1A1 and COL1A2." (PMID 31575827, 2019). "Mutations in COL1A1 were shown to be associated with osteoporosis and other bones disorders." (PMID 30382374, 2019). "Autosomal dominant mutations in COL1A1 are known causes of Ehlers-Danlos syndrome and osteoporosis." (PMID 29567674, 2018).